PHYH (phytanoyl-CoA 2-hydroxylase)
Description:
Catalyzes the 2-hydroxylation of not only racemic phytanoyl-CoA and the isomers of 3-methylhexadecanoyl-CoA, but also a variety of other mono-branched 3-methylacyl-CoA esters (with a chain length of at least seven carbon atoms) and straight-chain acyl-CoA esters (with a chain length longer than four carbon atoms). Does not hydroxylate long and very long straight chain acyl-CoAs or 2-methyl- and 4-methyl-branched acyl-CoAs.
Synonyms: PAHX; RD; PHYH1; LN1; LNAP1
Tractability: Small molecule: a structure with a bound ligand is known. PROTAC: ubiquitination databases record sites on it; its protein half-life has been measured.
Gene: Protein-coding gene on chromosome 10 (13,277,796 to 13,302,412, reverse strand). Ensembl gene ENSG00000107537.
Subcellular location: Peroxisome
Pathways (Reactome):
Protein localization: Peroxisomal protein import; TYSND1 cleaves peroxisomal proteins
Metabolism: Alpha-oxidation of phytanate
Gene Ontology:
Molecular function: carboxylic acid binding; ferrous iron binding; L-ascorbic acid binding; phytanoyl-CoA dioxygenase activity; protein binding; catalytic activity
Biological process: 2-oxoglutarate metabolic process; fatty acid alpha-oxidation; isoprenoid metabolic process; methyl-branched fatty acid metabolic process; 2-oxobutyrate catabolic process; fatty acid metabolic process
Cellular component: 9+0 non-motile cilium; peroxisome; cytosol; peroxisomal matrix
Genetic constraint (gnomAD): Loss-of-function variants: 21 observed, 26.37 expected, observed/expected ratio (o/e) 0.8, 90% interval 0.56 to 1.15. The upper end of that interval is the gene's LOEUF score, 1.15, which puts it in group 5 of 6, group 1 being the genes least tolerant of losing a copy. Missense variants: 287 observed, 308.74 expected, observed/expected ratio (o/e) 0.93, 90% interval 0.84 to 1.02. Synonymous variants: 130 observed, 119.03 expected, observed/expected ratio (o/e) 1.09, 90% interval 0.95 to 1.26.
Gene-disease validity (ClinGen):
ClinGen rates the evidence that PHYH causes each of these diseases.
phytanoyl-CoA hydroxylase deficiency (autosomal recessive): Definitive. Any disorder of peroxisomal alpha oxidation in which the cause of the disease is a mutation in the PHYH gene.
Homologues: Orthologues: chimpanzee PHYH (99% identical), macaque PHYH (95% identical), mouse Phyh (78% identical), rat Phyh (78% identical), pig PHYH (77% identical), guinea pig PHYH (77% identical), tropical clawed frog phyh (69% identical), dog PHYH (67% identical), zebrafish phyh (67% identical), Caenorhabditis elegans ZK550.6 (53% identical), Caenorhabditis elegans phyh-1 (44% identical).
Diseases named in the same sentence as PHYH in open-access papers:
PHYH is named in the same sentence as 37 diseases in open-access papers, as found by Europe PMC text mining. Sharing a sentence is not in itself a finding about the gene and the disease. The quoted sentences say what the papers report.
Refsum disease (22 papers, 2006 to 2025). Refsum disease, biochemically characterised by phytanic acid accumulation, belongs to the group of leucodystrophic diseases. "Mutations in the phytanoyl-CoA hydroxylase (PHYH) gene can lead to Refsum disease, which is characterised by the accumulation of phytanic acid due to its poor metabolism in peroxisomes." (PMID 40943222, 2025). "Genetically, Refsum diseases are related to the presence of biallelic variants in the PHYH (phytanoyl-CoA hydroxylase) gene, with a consequent failure to metabolize phytanic acid correctly." (PMID 40332750, 2025). "We note that Refsum disease is caused by mutations in the gene encoding phytanoyl-CoA hydroxylase (PHYH; MIM 602026), the mouse counterpart of which (Phyh) was excluded here." (PMID 36891866, 2023). "Refsum disease is caused by a deficiency of phytanoyl-CoA hydroxylase (PhyH) due to mutations in the PHYH gene, i.e., an inability to degrade the branched-chain fatty acid, phytanic acid." (PMID 37759536, 2023). "PHYH has been proven to be linked to multiple diseases, such as Refsum disease and retinitis pigmentosa, and can serve as a prognostic marker in clear cell renal cell carcinoma." (PMID 36818393, 2023). "The expression of PHYH has been linked to multiple diseases such as Refsum Disease and Retinitis Pigmentosa." (PMID 33468235, 2021). "Refsum disease (OMIM #266500) is caused by mutations in the PHYH gene encoding phytanoyl-CoA 2-hydroxylase, which is a crucial enzyme in peroxisomal α-oxidation." (PMID 29209936, 2018). "Of note, Refsum's disease is caused by mutations to the PHYH gene, which is responsible for the metabolism of a dietary branched chain fatty acid, phytanic acid, through its α-oxidation in the peroxisomes." (PMID 30237167, 2018). "Another example is a highly variable tandem duplication of the PHYH gene, which in humans is linked to Refsum disease, with multiple epiphyseal dysplasia among variable features." (PMID 29258433, 2017). "Mutations in the PHYH gene have been established as the genetic cause for classical Refsum disease (MIM #266500)." (PMID 26686055, 2016). "For example, Refsum disease is an autosomal recessive disorder in humans that can result from mutations in the PHYH gene and subsequent accumulation of phytanic acid in tissues." (PMID 20932325, 2010). "• Adult Refsum disease caused by mutation in the gene encoding phytanoyl-CoA hydroxylase (PAHX or PHYH) or the gene encoding peroxin-7 (PEX7) presents with highly elevated phytanic acid, anosmia, deafness, and RP." (PMID 17032466, 2006). "Several of these genes are implicated in systemic disorders that can feature retinal involvement, including KIF11 (microcephaly–lymphedema–chorioretinal dysplasia), COL11A1 (Stickler syndrome), PHYH (Refsum disease), and TUBB4B (Leber congenital amaurosis with early-onset deafness)." (PMID 40923693, 2025).
retinitis pigmentosa (4 papers, 2021 to 2024). Retinitis pigmentosa (RP) is an inherited retinal dystrophy leading to progressive loss of the photoreceptors and retinal pigment epithelium and resulting in blindness usually after several decades. "We recruited patients from Moorfields Eye Hospital (London, UK) and Buenos Aires, Argentina, who were diagnosed with retinitis pigmentosa and found to have biallelic variants in PHYH, with at least one being c.678+5G>T." (PMID 38411969, 2024).
Ataxia (2 papers, 2013 to 2020). Ataxia refers to impaired coordination of voluntary muscle movement. "We, therefore, supplemented the EOAD- control group with ataxia genotypes that were not reported with comorbid dystonia in literature (including ABHD12; IFRD1; KIAA0226; PHYH; TDP1; VWA3B; GTF2H5; FLVCR1; ACO2; HSD17B4; DNAJC3 gene mutations; PubMed and OMIM)." (PMID 33255407, 2020).
clear cell renal cell carcinoma (2 papers, 2021 to 2023). "This study attempts to evaluate the prognostic role of PHYH for overall survival (OS) in clear cell renal cell carcinoma (ccRCC) by means of publicly available data from The Cancer Genome Atlas (TCGA)." (PMID 33468235, 2021).
peroxisomal disease (2 papers, 2020 to 2022). A group of congenital disorders of lipid metabolism, caused by loss of the normal peroxisomes. "This is an autosomal recessively inherited peroxisomal disease due to biallelic variants in PHYH (>90%, encodes phytanoyl-CoA hydroxylase." (PMID 32752260, 2020).
heart failure (1 paper, 2024). Inability of the heart to pump blood at an adequate rate to meet tissue metabolic requirements. "Single enzyme defects in peroxisomal α- and β-oxidation, including the PTS2-proteins, PHYH, and ACAA1, cause toxic levels of BC/VLCFAs leading to heart failure." (PMID 38365851, 2024).
Hyperglycemia (1 paper, 2020). An increased concentration of glucose in the blood. "In our study, hyperglycemia was associated with high levels of IL-33 in cell lysates, the effects being attenuated by quercetin, both doses of PhyH and low doses of PhyF." (PMID 32824505, 2020). "A similar effect was noticed in the incubation of cells with two doses of PhyH extract in hyperglycemia (p < 0.001)." (PMID 32824505, 2020). "In hyperglycemia, the inhibitory effect on IL-33 secretion was noticed after a low dose of PhyF extract and after both doses of PhyH." (PMID 32824505, 2020). "Thus, PhyH, PhyF and quercetin increased MDA and TNF-α levels in normoglycemia while in hyperglycemia they exerted protective effects against oxidative stress and inflammation." (PMID 32824505, 2020).
Obesity (1 paper, 2025). Accumulation of substantial excess body fat. "With respect to obesity phenotypes, we detected a significant reduction in body weight gain in the PhyH (p < 0.05) and PhyL (p < 0.05) groups without changes in food intake." (PMID 40097405, 2025).
renal carcinoma (1 paper, 2021). A carcinoma arising from the epithelium of the renal parenchyma or the renal pelvis. "Although there are no study associating human cancers to PHYH expression, The Human Protein Atlas have reported it to be a prognostic marker in renal cancer." (PMID 33468235, 2021).
sarcopenia (1 paper, 2026). Progressive decline in muscle mass due to aging which results in decreased functional capacity of muscles. "Collectively, these findings suggest that fatty acid metabolism may play an important role in the shared molecular features between UC and sarcopenia, and that PHYH may serve as potential diagnostic biomarkers." (PMID 42064059, 2026).
cancer (6 papers, 2018 to 2025). A tumor composed of atypical neoplastic, often pleomorphic cells that invade other tissues. "We demonstrated that a decrease PHYH expression is associated with presence of tumor, grade of cancer, stage of cancer, primary size of tumor, age, and presence of distant metastasis." (PMID 33468235, 2021). "The expression levels of PHYH in various cancers were shown including ccRCC with p < 0.001." (PMID 33468235, 2021). "In addition, decreased expression of PHYH correlated significantly with grade of cancer cells (G1-2 vs. G2-4, p = 0.025), the Union for International Cancer Control (UICC) stage (Stage I&II vs. Stage III&IV, p = 5.604e−05), and size of primary tumor (T1-2 vs. T3-4, p = 4.373e−05)." (PMID 33468235, 2021). "However, ARSI and PHYH have not been previously studied in cancers." (PMID 33277966, 2021).
tumor (2 papers, 2011 to 2021). "However, there exists a significant gap in knowledge in the role of peroxisome and its associated gene PHYH in the potential of tumor induction and development." (PMID 33468235, 2021). "Other clinicopathologic variables associated with poor survival include age, grade, UICC stage, size of primary tumor, and PHYH expression." (PMID 33468235, 2021). "Expression of PHYH is significantly lower in patients with tumor (p = 1.156e−19 & p = 2.634e−10)." (PMID 33468235, 2021). "The abnormal expression of PHYH in our tumor cells activates the immune checkpoint." (PMID 33468235, 2021). "Classic univariate ROC curve analysis was performed to assess true-positive rate and false-positive rate of the PHYH expression between adjacent non-neoplastic kidney tissue and tumor based on the are under the curve (AUC)." (PMID 33468235, 2021).
PHYH also shares sentences with these, for which no sentence is quoted: prostate carcinoma (3 papers); Anosmia (2); biliary tract cancer (1); breast tumors (1); cardiomyopathy (1); Cholecystitis (1); colon tumors (1); deafness (1); diabetes (1); Dystonia (1); glioma (1); hepatoma (1); ichthyosis (1); Leber congenital amaurosis with early-onset deafness (1); lupus nephritis (1); lymphedema (1); metabolic disorders (1); metabolic syndrome (1); microcephaly (1); multiple epiphyseal dysplasia (1); neurodevelopmental disorder (1); ovarian carcinoma (1); Pitt-Hopkins syndrome (1); renal failure (1); Stickler syndrome (1).